CCL3 (C-C motif chemokine ligand 3)
Diseases named in the same sentence as CCL3 in open-access papers (continued):
Sharing a sentence is not in itself a finding about the gene and the disease.
infection (continued). "However, IFI16 knockdown did not consistently reduce CCL3 protein levels after 20 h of infection (data not shown)." (PMID 23062757, 2012). "Acute HIV infection also induces production of chemokines (CCL2, CCL3, CCL4, and CCL5), which may recruit uninfected monocytes/macrophages and/or CD4+ T lymphocytes to the sites of virus replication, thus promoting the spread of infection and/or the establishment of virus reservoirs." (PMID 40507836, 2025). "Additionally, CD8+CTLs release CCL3 (macrophage inflammatory protein-1α or MIP-α) and CCL4 (MIP-1β), which may further optimize local Ag presentation by increasing APC infiltration at the infection/inflammatory site." (PMID 41009359, 2025). "Therefore, CCL3 may drive full activation/differentiation, as acquisition of CCR5 on cell surface in peripheral tissues and may also coordinate the migration of inflammatory CCR5+ CD8+ T-cells to the heart tissue in chagasic infection." (PMID 32194558, 2020). "Moreover, blockage of CCL3 with a neutralizing antibody showed no change in the recruitment of NK cells and did not affect viral loads in the lungs of hRSV-infected mice after 4 days of infection." (PMID 30936869, 2019). "In our study, BVDV-2 infected goat PBMCs showed increased transcription of CCL3, CCL4, CCL5, CCL20, CXCL10 and decrease of CCL2, suggesting that such chemokines may contribute to the recruitment and regulation of macrophages or other inflammatory cells to the infected sites after infection." (PMID 31226933, 2019). "Consequently, CCL2, CCL3, and CCL9 produced by HSPCs may activate and attract neutrophils, monocytes and dendritic cells, therefore contributing to another level of protection against infection." (PMID 30234030, 2018). "Besides chemokines, cytokines such as TNF-α are released acutely in response to injury or infection, and function to initiate and maintain the inflammatory process in part by stimulating other pro-inflammatory cytokines (e.g., IL-1α, IL-1β, and IL-6) and chemokines (e.g., CCL2, CCL3, and CXCL2)." (PMID 26860080, 2016). "CCL3 (MIP-1α) and CCL5 (RANTES) were observed in all pre- and post-infection sera without any specific change in expression level (data not shown)." (PMID 35371043, 2022). "T. denticola single species implant infections systemically increased IL-6, IL-13, CXCL1/KC, CCL-3/MIP1α, and CCL2/MCP compared to tissue infection without the implant." (PMID 35203495, 2022). "A. actinomycetemcomitans infection of implants caused a significant increase in the systemic expression of IL-2, IL-3, IL-5, CCL-3/MIP1α, and CCL2/MCP-1 compared to tissue infections without implants." (PMID 35203495, 2022). "Infection of female mice with M. circinelloides but not males resulted in increased levels of CCL2, CCL3 and CCL4." (PMID 33919611, 2021). "In comparison with non-infected (NI) mice, increased expression of CCL3 mRNA transcripts was detected in the heart tissue of acutely infected C57BL/6 ccl3+/+ mice at 28 dpi and persisted during the chronic phase of infection (120 dpi)." (PMID 32194558, 2020). "We also found that protein levels of IL-6, IL-12p40, IL-12p70, CCL2, CCL3 and CCL4 were not suppressed in response to rosiglitazone treatment during super-infection." (PMID 31159430, 2019). "In contrast to these findings, infection with the hRSV Long strain in NHBEs cells did not lead to the secretion of CCL2 and CCL3, but the levels of CCL5 were increased as compared to uninfected cells." (PMID 30936869, 2019). "Ccl3 is elevated in response to ANDV infection, but not SNV infection, whereas Cxcl2 levels are similarly elevated with MAPV and SNV infection, but much higher in ANDV infection." (PMID 27763552, 2016). "When mice were depleted of neutrophils at 8 weeks post-infection and evaluated at 12 weeks post-infection, they showed significant decrease in levels of CCL3 (MIP-1α), CCL4 (MIP-1β), CXCL1 (KC), LIF, G-CSF and M-CSF (Data not shown)." (PMID 27690127, 2016).
infection (continued). "CCL-3 and CCL-4 levels were significantly upregulated by in vitro infection with R5 HIV-1 but not X4." (PMID 21767373, 2011). "Plasma levels of MIP-1α/CCL3 have also been investigated and reported in several studies of S mansoni infected humans, murine models and cell culture infections, but none for S. haematobium." (PMID 19852800, 2009). "Of the 21 analytes that were evaluated, 9 analytes (angiopoietin, CCL3, CCL5, CCL7, CCL12, CXCL10, and TNF-α) were significantly changed in response to infection in both non-pregnant and pregnant mice, and more robust response was, in general, noted in non-pregnant mice (p < 0.05)." (PMID 38104118, 2023). "A non-significant decrease in MIP-1α/CCL3, MIP-1β, RANTES/CCL5 and MCP-1 was observed in negative post-infection samples, which could be related to the resolution of the inflammatory response." (PMID 36482106, 2022). "Interestingly, we found differences in the expression of several immune-barrier molecules (filaggrin, MIP-1α/CCL3, MIP-1β/CCL4 and MCP-1) in NPA supernatants of virus-negative controls compared to negative pre-infection samples of RVI neonates." (PMID 36482106, 2022). "The addition of IFNγ after infection not only resulted in a dramatic increase of the translation of the before mentioned genes but also in the translation of IFNß1, IL12ß, MIP1 and CCL3, CCL4, NOS2 and SOD2, and FAS but, nevertheless, did not prevent multiplication of the bacteria." (PMID 32462327, 2020). "In the mutant strain infection, we noted that Th17-related cytokines (IL-17A, IL-22) and neutrophil-related chemokines (CCL2, CCL3, CXCL1, CXCL2) are significantly reduced at the early stage of infection, which might be related to the absence of melanin and defects in growth and germination." (PMID 35696422, 2022). "Following CB4 challenge, TLR3KO mice produced similar levels of CCL2 and CXCL9 while levels of CCL3 and CCL4 were slightly reduced but were not significantly different from either WT NOD controls or MyD88KO mice suggesting that these chemokines are not critical for survival following infection." (PMID 19122812, 2009). "Interestingly, the SARS‐CoV‐2 peptides which exhibited sequence similarity with CCL3 and CCL3L1 (and CD163) were not homologous with HCoVs —which may increase the likelihood of being involved in immunopathology after infection." (PMID 35143694, 2022).
tumor (697 papers, 2004 to 2026). "Overall, cells secreting CCL3 were linked to reduced tumor growth, and treatments like the IL3 vaccine or bolus rCCL3 therapy showed promise in reducing tumor growth." (PMID 41153795, 2025). "In contrast, in tumor-bearing subjects, elevated CCL3 is often linked to disease progression, particularly through mechanisms like enhanced angiogenesis, recruitment of immunosuppressive cells, and sustained inflammation." (PMID 41153795, 2025). "The reduction in the tumor formation in CCL3/CCR5 deficient mice co-occurred with the reduction in AOM/DSS-induced type I collagen-positive fibroblast accumulation." (PMID 41153795, 2025). "Their main focus of investigation was on cancer-associated fibroblasts (CAFs) that accumulate at tumor site through the interaction between CCL3 and CCR5." (PMID 41153795, 2025). "Among other notable DEGs, PD-L1+ clusters were also defined by high expression of many transcripts encoding for chemokines that have been shown to be released by suppressive tumor-associated neutrophils such as Ccl2, Ccl3, Ccl4, Ccl5, Ccl12, Ccl17, and Cxcl16." (PMID 39392875, 2024). "These two populations expressed genes Cxcl3, Ccl3, Ccl4, Atp6v1c1, Atp6v0d2, which have been associated with a tumor promoting phenotype." (PMID 38265267, 2024). "The C‐C motif chemokine ligand 3 (CCL3) is a chemokine that plays a key role in the formation of tumour immune microenvironment and tumour‐associated macrophages (TAMs) polarization." (PMID 37775993, 2023). "At the same time, there was an upregulation of genes coding chemokines, e.g., Ccl3, Ccl4 previously linked to the attraction of T cells to the tumor bed36." (PMID 35760796, 2022). "Deficiency of the CCL3/CCR5 system resulted in a remarkably decreased tumor formation and lung metastasis." (PMID 32349303, 2020). "CCL3 is secreted by the tumor, which causes an increase in CCL2, CCL7, and CCL8 expression in the lungs and brain, which facilitates the metastasis to these organs." (PMID 33076281, 2020). "These were retained within the tumour by CCL3, a chemokine produced by metastasis-associated macrophages through the activation of the CCL2 receptor (CCR2)." (PMID 28193698, 2017). "Genetic loss of host CCL3 or its receptor CCR1 reduces the MAM accumulation in the tumor-challenged lung 24 h after tumor injection and decreases number of metastatic foci." (PMID 26275794, 2015). "The upregulation of genes implicated in anti- tumor immune responses was observed, including CCL3 (Chemokine Ligand 3), the Natural Killer cell ligand; ULBP2 and IL24." (PMID 26304929, 2015). "CCL3 is, interestingly, produced at high levels by tumor-associated DCs (unpublished observations), and therefore abundantly over-produced in the tumor microenvironment." (PMID 21113407, 2010). "Because CCL3 expression was strongly associated with immune modulation within the tumor microenvironment, this pointed out that CCL3 could serve as a promising therapeutic target with significant implications for immunotherapy and chemotherapy response." (PMID 42004887, 2026). "Furthermore, CCL3, secreted by monocytes and macrophages, is implicated in TAMs promotion of tumor cell proliferation and development." (PMID 39953613, 2025). "Similarly, CCL3 (macrophage inflammatory protein-1 α), a pro-inflammatory chemokine implicated in tumor metastasis, was highly expressed in Met2 cells." (PMID 39996058, 2025). "CCL3, the second-most frequently found cytokine in our cohort, is an inflammatory cytokine, secreted by monocytes and macrophages, having a fundamental role when tumor-associated macrophages have an impact on tumor development." (PMID 40869066, 2025). "Regarding the pro-tumorigenic role, studies have shown that the expression of chemokines such as CCL2 and CCL3 can recruit tumor-associated macrophages (TAMs) of the M2 subtype to the tumor microenvironment (TME), thereby enhancing the progression of ductal carcinoma in breast tissue." (PMID 39769501, 2024).
tumor (continued). "Although CCL3 (blue box) was linked to anti-tumor effects, its role in PDA is unclear." (PMID 37563620, 2023). "We were not able to demonstrate a direct effect of the drug on key immune cells in vitro since, e.g., the inflammatory cytokine Ccl3 (mainly produced by macrophages) was downregulated in MePip-SF5-treated mice but upregulated in M2-polarized (tumor-associated) macrophages in vitro." (PMID 37998354, 2023). "Further, CCL3 is upregulated in tumor-associated macrophages (TAMs)." (PMID 35008176, 2021). "SCC tumor formation is reduced in CCL3 and CCR5 deficient mice." (PMID 32158692, 2020). "Using a mouse model, we show in this article that intravenous administration of a human CCL3 variant carrying a single amino acid substitution after mild local hyperthermia not only induces tumor growth inhibition at the treated site but also inhibits metastasis." (PMID 31717914, 2019). "E7046 + E7777 treatment activated the innate immune system which led to an “inflamed” TME evidenced by expression of genes encoding Ccl5/RANTES, macrophage inflammatory protein-1α (MIP-1α/Ccl3), Cxcl9, Cxcl10, and Cxcl11, previously found associated with tumor destruction." (PMID 28920002, 2017). "Similarly to our findings, previous studies found that deficiency of the CCL3/CCR5 system resulted in a significantly reduced tumour formation and a reduced lung metastasis." (PMID 28881626, 2017). "The sMSC-derived CCL3 may also help to promptly create a beneficial environment for immunoevasion of tumor cells by recruiting the cancer-associated CCR5+ Tregs, although not yet investigated in our study." (PMID 25883937, 2015). "On the other hand, Jun can stimulate apoptosis in a range of cancer cell types and play a tumour-suppressing role, for example, in a manner inversely related to JunD or by transcriptional regulation of senescence- and inflammation-associated genes including IL-1β, TNFα, CCL3 and CCL8." (PMID 39859271, 2025). "Therefore, CCL3/VIRMA/SIRT1 axis may be one of the important mechanisms underlying tumor evolution and metastasis and is a potential new therapeutic target for ICC." (PMID 36691046, 2023). "Serum CCL3 concentrations were significantly elevated in ccRCC patients compared to controls and increased with tumor grade, with the highest levels observed in patients with advanced disease (G3+G4)." (PMID 41828706, 2026). "For example, Cr3+ can increase the expression of CXCL13 and CCL3 chemokines, thereby generating tertiary lymphoid structures in tumor, which promotes the infiltration, migration, and anti-tumor efficacy of CAR-T cells." (PMID 41355954, 2026). "Single-cell analysis revealed that the pretreatment tumor microenvironment of responders was significantly enriched with a proinflammatory neutrophil subset characterized by high expression of CCL3 (Neu_CCL3)." (PMID 41817286, 2026). "Polarized M1-like macrophages secreted chemokines (CCL5 and CCL3), which facilitated T lymphocyte infiltration into the tumor bed." (PMID 41029711, 2025). "Basophils facilitated the infiltration of CD8+ lymphocytes into the tumor through the production of chemokines CCL3 and CCL4." (PMID 40136652, 2025). "Correspondingly, CCL3 expression in primary human CRC tissue generally increased with advancing tumor stage." (PMID 41153795, 2025). "Altogether, this study showed that the MK2 pathway regulates the production of CCL3, which increases tumor cell proliferation and induces the production of other cytokines." (PMID 41153795, 2025). "The results revealed that CCL5 and CCL3 were positively correlated with tumor infiltrating CD8+ T cells in BC." (PMID 41029711, 2025). "The trivalent Cr3+ ions, which are the major degradation product of these nanocomposites, can increase the CXCL13 and CCL3 chemokine expressions to generate tertiary lymphoid structures (TLSs) in the tumor tissues, facilitating the CAR‐T cell infiltration." (PMID 38899741, 2025).
tumor (continued). "As the tumor progressed, pro-inflammatory neutrophils (i.e. Ccl3- and Mmp8+ neutrophils) infiltrated the TIME of the SC models, whereas angiogenic neutrophils (i.e. Myo1e+ neutrophils) remained the predominant type of immune cell in the TIME of the BOT models." (PMID 40899264, 2025). "PLAT, a secreted serine protease, has been demonstrated to enhance cancer cell migration and invasion, whilst CCL3, a gene coding for a ligand for CC motif chemokine receptor 1 and 5 (CCR1 and CCR5), has been implicated in promoting tumour growth." (PMID 40998421, 2025). "CC chemokines such as CCL1, CCL2, CCL3, CCL21 and CCL25 are also associated with invasion and migration in many tumours." (PMID 40852716, 2025). "The CCL2-induced CCL3 cascade also prolongs the retention time of MAMs at the tumor site, thereby accelerating the extravasation of tumor cells." (PMID 41341593, 2025). "First, we did not perform depletion experiments to confirm the contribution of NK cells and CCL3 in the anti-tumor activity in vivo." (PMID 40551137, 2025). "DGE analysis revealed that liver Tregs, compared to tumor and PBMC Tregs, had higher expression of key genes linked to Treg recruitment and immune suppression (e.g., CXCR3, CCL3, CCL4, and CCL5)." (PMID 40848148, 2025). "Natural killer (NK) cells seem to be a major lymphocyte subtype recruited predominantly to the CCL3-rich tumor site." (PMID 41153795, 2025). "For example, in the B16.F10 murine melanoma model, TLR2 agonists stimulate the release of MC-derived interleukin-6 and CCL3, which directly inhibit tumor growth and indirectly facilitate the recruitment of natural killer cells (NKs)." (PMID 41425713, 2025). "We found that these SPP1 positive myeloid cells (Macro_SPP1/CCL3 and Macro_SPP1) resembled the pro-tumor macrophages in a CXCL9-SPP1 macrophage polarity system, a new human cancer dataset based classifying system to replace M1-M232." (PMID 40883281, 2025). "This is because reduced CCL3 expression would favor the pro-tumor M2 macrophages, which suppress immune responses and promote tumor growth and metastasis." (PMID 40484866, 2025). "A previous study from our laboratory demonstrated that macrophage inflammatory protein 1-alpha (CCL3) mediates tumor growth, progression, and bone destruction in MM." (PMID 39953613, 2025). "By recruiting immunosuppressive cells such as M2-type macrophages and Treg cells, CCL3 can promote immune evasion during tumor immune escape." (PMID 41376630, 2025). "In glioma macrophages, CCL3 is a marker of the anti-tumor fraction, while CD68 and CD163 are markers of the pro-tumor fraction." (PMID 40191211, 2025). "Concurrently, N1 TANs amplify anti-tumor immunity by recruiting CD8+ T cells via chemokines such as CXCL10 and CCL3, facilitating antigen-specific tumor clearance." (PMID 41438763, 2025). "In CRC, CCL3 is frequently upregulated, promoting tumor proliferation, invasion, and immune remodeling through CCR5- and MAPK-dependent pathways." (PMID 41153795, 2025). "Because CCL3, CCL4, and CCL5 signal through the CCR5 receptor, we next evaluated LLC tumor growth in CD8+ T cell–sufficient and –deficient mice treated with the FDA-approved CCR5 antagonist, maraviroc." (PMID 40553564, 2025). "In this study, elevated CCL3 levels were exploited by increasing the matching chemokine receptor on CIK cells to enhance their tumor-targeted trafficking." (PMID 41153795, 2025). "Numerous studies revealed that chemokines such as CXCL1, CXCL2, IL-8 (CXCL8), CXCL5, CXCL12, CCL2, and MIP-1α (CCL3) promote the infiltration of neutrophil to the tumoural microenvironment." (PMID 40852716, 2025).